LCE1B (late cornified envelope 1B)
Description:
Precursors of the cornified envelope of the stratum corneum.
Synonyms: LEP2; SPRL2A
Tractability: No criterion of Open Targets' tractability assessment is met for any kind of drug.
Gene: Protein-coding gene on chromosome 1 (152,811,971 to 152,813,108, forward strand). Ensembl gene ENSG00000196734.
Pathways (Reactome):
Developmental Biology: Formation of the cornified envelope
Gene Ontology:
Molecular function: identical protein binding; protein binding
Biological process: epidermis development
Genetic constraint (gnomAD): Loss-of-function variants: 3 observed, 2.78 expected, observed/expected ratio (o/e) 1.08, 90% interval 0.46 to 1.88. That is too few expected variants to judge how well the gene tolerates losing a copy. Missense variants: 151 observed, 147.91 expected, observed/expected ratio (o/e) 1.02, 90% interval 0.89 to 1.17. Synonymous variants: 56 observed, 57.59 expected, observed/expected ratio (o/e) 0.97, 90% interval 0.78 to 1.22.
Homologues: Orthologues: chimpanzee LCE1B (97% identical). Paralogues in human: LCE1C (97% identical).
Diseases named in the same sentence as LCE1B in open-access papers:
LCE1B is named in the same sentence as 3 diseases in open-access papers, as found by Europe PMC text mining. Sharing a sentence is not in itself a finding about the gene and the disease. The quoted sentences say what the papers report.
psoriasis (1 paper, 2017). An autoimmune condition characterized by red, well-delineated plaques with silvery scales that are usually on the extensor surfaces and scalp. "Within the keratinocyte differentiation signature subgroup that is down‐regulated in psoriasis, several genes, such as LCE1B, LCE2B, FLG2, and LOR, are known to be associated with the terminally differentiated keratinocytes (cornecytes) that make up the stratum corneum." (PMID 28008606, 2017).
psoriasis vulgaris (1 paper, 2018). Plaque psoriasis is the most common presentation of psoriasis. "This study aimed to investigate the association between the gene polymorphisms of LCE1B, LCE1C, LCE3A, LCE3D and psoriasis vulgaris among Mongolians from Inner Mongolia." (PMID 29397434, 2018).
cancer (1 paper, 2021). A tumor composed of atypical neoplastic, often pleomorphic cells that invade other tissues. "LCE1B is the only transcript that increased as cancer stages advanced." (PMID 34944802, 2021).